ZEB1 (zinc finger E-box binding homeobox 1)
Diseases named in the same sentence as ZEB1 in open-access papers (continued):
Sharing a sentence is not in itself a finding about the gene and the disease.
tumor (continued). "In addition to downregulating epithelial genes, ZEB1 represses basement membrane synthesis, enhances collagenous matrix production, and activates the transcription of matrix metalloproteases (MMP) 1, 9, and 14, thus promoting extracellular matrix remodeling and tumor cell invasion." (PMID 35454770, 2022). "In addition, VWCE promotes tumor cell migration and invasion through EMT, as VWCE overexpression leads to decreased levels of N-cadherin, vimentin, and the EMT-induced transcription factor, ZEB1, as well as elevated E-cadherin levels, indicating a significant inhibition of EMT processes." (PMID 33194737, 2020). "Similarly, ALDH3A1 is associated with the overexpression of NFkB and EMT markers such as VIM, FN1, and Zeb1, revealing that the enzyme, through a direct effect on the redox state of tumor cell metabolism, is involved in the process that links stemness, EMT, and inflammation in tumor cells." (PMID 31817719, 2019). "Thus, a reciprocal negative feedback loop involving ZEB1 and miRNA expression may tightly control tumor metastasis." (PMID 30813457, 2019). "MTT and cell invasion assays showed that knockdown of ZEB1 by the introduction of ZEB1 siRNA suppressed MG63 and HOS cell proliferation (P < 0.05) and invasion (P < 0.05), suggesting that negative regulation of ZEB1 may mediate the tumor suppressive effects of miR-409-3p in OS cells." (PMID 30846940, 2019). "miRNA 200 family targets ZEBs and regulates negative tumor development and EMT, whole-genome miRNA analysis of GBM shows that loss of miRNA200c expression is related with EGF receptor (EGFR) amplification and ZEB1 overexpression, suggesting the involvement of ZEB1 in tumor aggressiveness." (PMID 29642503, 2018). "Finally, to test whether ZEB1 is expressed by cells of the tumor microenvironment, co-staining of ZEB1 with markers of immune and glial cells were performed in non-tumor tissue." (PMID 28945795, 2017). "Thus both tumor cells and reactive astrocytes, but not immune cells stain ZEB1-positive." (PMID 28945795, 2017). "While we show that ZEB1 KO in fibroblasts does not lead to significant changes in markers of EMT, others have shown that silencing ZEB1 in tumor cells can actually revert EMT, thereby reducing tumor aggressiveness." (PMID 41244268, 2025). "In addition, FBXO32-mediated epithelial-mesenchymal transformation (EMT) enhances the expression of Snail and ZEB1 through CtBP1 ubiquitination in breast cancer, which not only promotes tumor metastasis, but also upregulates PD-L1 and attracts MDSCs, further weakening the anti-tumor immune response." (PMID 40534867, 2025). "Third, decreased expression of individual tumor-intrinsic mesenchymal markers was confirmed in HER2 positive biopsies; mesenchymal markers such as CDH2, ZEB1, and SNAI1 showed higher expression in the HER2 negative cohort (p < 0.001)." (PMID 39151279, 2024). "Here tumour growth was strongly enhanced by ferrostatin-1 for MDA-MB-231 wild-type cells, indicating spontaneous ferroptosis, but not for Zeb1-depleted cells (shZeb1)." (PMID 39009641, 2024). "Both canonical and non-canonical isomiRs targeted well-known drivers of tumor progression, including master regulators of epithelial-mesenchymal transition (EMT), such as ZEB1 and ZEB2 (see ‘Discussion’ for details)." (PMID 36275459, 2022). "There was no delay in tumor onset in KPPC mice compared to KPPC with heterozygous Zeb1 deletion (KPPC;ZF+) or homozygous Zeb1 deletion (KPPC;ZcKO) as measured by the emergence of a first palpable pancreatic nodule." (PMID 33852841, 2021). "Statistically significant differences in co-expression of PRMT1 with ZEB1, RUNX1 and TWIST1 were observed only in ccRCC, but not in other analyzed tumor types." (PMID 31655611, 2019). "Homogenous positive or homogenous negative PRMT1 and ZEB1 expression on TMA, corresponded to the same staining pattern on whole-mount section, regardless of the tumor type or nuclear grade." (PMID 31655611, 2019).
tumor (continued). "Decision curve analysis confirmed that ZEB1 status with or without IDH1 was more beneficial to clinical decision making than conventional information such as age and tumor grade." (PMID 30705664, 2018). "ZEB1 knockdown alone was as efficient as vemurafenib treatment in decreasing SKMEL5 xenografted tumor growth, but the combined inhibition of BRAF and ZEB1 did not lead to a further significant decrease in tumor growth (Fig EV4D)." (PMID 27596438, 2016). "Their half-lives in the carcinoma cell line H1299 were longer than those in the non-malignant tumor cell lines A549, supporting the concept that EMT-TFs (Zeb1/2) are more stable in the carcinoma cell lines." (PMID 25460509, 2015). "The coordinated upregulation or, not uncommonly, overexpression of ZEB1, ZEB2, SNAI1, and VIM and the downregulation of CDH1 indicated that EMT was under way, making the tumor cells assume a mesenchymal phenotype." (PMID 25157365, 2014). "Here, tumor formation, invasion and resistance are not independent but intertwined processes regulated by the EMT activator ZEB1." (PMID 23818228, 2013). "ZEB1 positive tumours showed a significant enrichment for PCNA and EGFR, while NF1 deletions were significantly more prevalent in ZEB1 negative specimens." (PMID 23818228, 2013). "Moreover, ZEB1 plays a crucial role at the forefront of tumor invasion, and CD73 is involved in regulating ZEB1 non-coding RNA through its 3’UTR, which in turn affects the progression of PTC." (PMID 40530008, 2025). "Ectopic expression of ZEB1 significantly reduced the ferroptosis defense of 2D but not 3D CRCs, while silencing ZEB1 or ZEB2 promoted the antiferroptosis ability of both 2D and 3D tumor cells." (PMID 39985376, 2025). "However, the immunohistochemical (IHC) detection of ZEB1 in SACC tumor parenchyma did not depict any positive reaction, while positive staining was examined in the tumor stroma at the level of CAFs and endothelial blood cells in all cases." (PMID 37296849, 2023). "The transcription factor ZEB1 is perhaps best known for its role in EMT; however, it is also important for functions not related to EMT that may be even more critical for tumor progression." (PMID 35027548, 2022). "ZEB1 expression was not altered after romidepsin treatment in cells; ZEB1 expression could not be observed in treated TU-BcX-4IC spheres, PDX-Os, nor tumor implants due to low endogenous transcript levels." (PMID 33035223, 2020). "Moreover, targeting the MMP9-PAR1 axis in ZEB1-silenced cells did not further affect cell viability, confirming that MMP9-PAR1-dependent mesenchymal transition is the mechanism by which tumor cells escape macrophage-dependent cytotoxicity." (PMID 32809114, 2020). "In addition, this primary cell cultures were from PCa primary tumor, like 22Rv1 cell line (but this last were immortalized) that neither shown a SDC-1 repression with the ZEB1 over expression." (PMID 30065348, 2018). "For instance, it was reported that microRNA-200/Zeb1 axis could regulate PD-L1 expression even in the absence of IFN-γ in lung tumor cells and tumor cells with mesenchymal phenotype are intrinsically capable of immunosuppressing." (PMID 30456206, 2018). "To further confirm whether or not HS-173 inhibits tumor growth through the regulation of EMT, we identified the expression levels of Ecadherin, Vimentin, ZEB1 along with p-AKT and p-Smad2." (PMID 27793006, 2016). "Notably, other important EMT-related markers such as SNAI1, SNAI2, ZEB1, ZEB2 and TWIST1 at the invasive tumor front were not thoroughly examined in these reported studies." (PMID 26214683, 2015).
tumor (continued). "In fact, TGF-β, which is well present in the GBM environment and secreted by microglia, stromal and tumor cells, is able to induce the mesenchymal transition, via SMAD2 phosphorylation and recruitment of ZEB1, especially in GBM with a low or absent expression of mesenchymal markers." (PMID 26078762, 2015). "In this regard, we discovered an important function of ZEB1 in macrophages to limit tumor and lung metastatic growth by cytokine-mediated CTL recruitment in syngeneic models of two gastrointestinal tumor entities, without direct noticeable effects on tumor cells." (PMID 40595293, 2025). "The results could be confirmed in an ex vivo mouse model, where tumours from implanted cells grew in the tissue context of precision-cut lung slices, and only for wild-type Zeb1, but not for Zeb1-depleted cells, SCD inhibition cooperated with ML210 to reduce tumour growth by ferroptosis." (PMID 39009641, 2024). "In addition, tumor microenvironmental signals such as TGFβ could switch cancer cell states between non-CSC and CSC by controlling the ZEB1 promoter." (PMID 35646083, 2022). "In addition, we found that the plasticity of UM cells featured as vascular mimicry, a flexible phenotype of tumor cells capable of recapitulating vascular channels without endothelial cells and pericytes and expressing CD34 and VE-cadherin, can be promoted by ZEB1." (PMID 35404029, 2022).
cancer (1,375 papers, 2008 to 2026). A tumor composed of atypical neoplastic, often pleomorphic cells that invade other tissues. "According to studies, a poor patient prognosis is linked to increased ZEB1 expression, which also positively correlates with cancer invasion and metastatic potential." (PMID 40918458, 2025). "For example, EVs from cancer-associated fibroblasts carry transcription factors like SNAI1/ZEB1 or miRNAs (e.g. miR-193a, miR-210 from bone marrow cells) that prime lung cells for invasiveness (via STAT3, Wnt, TGF-β pathways)." (PMID 41311647, 2025). "As a transcription factor implicated in EMT, ZEB1’s overexpression serves as a predictor of poor survival outcomes in various cancers." (PMID 40771411, 2025). "ZEB1, which can bind to nearly 2000 genes, is associated with increased cancer cell migration, survival, and invasion." (PMID 39615277, 2025). "Deletion or modification of genes associated with EMT, such as Snail, Twist, and ZEB1, can reverse the mesenchymal phenotype of cancer cells, making them more responsive to treatment." (PMID 40895189, 2025). "ZEB1 has been implicated in acting in the invasive front of tumors, not only through its induction in cancer cells of a motile dedifferentiated phenotype, but also via differential regulation of genes involved in stromal remodeling." (PMID 38388432, 2024). "In summary, different ways of EMT activation in cancer cells increase ferroptosis sensitivity for which the EMT-TF Zeb1 is a crucial underlying factor." (PMID 39009641, 2024). "In summary, our study has identified ZEB1 as a pivotal biomarker associated with cancer prognosis and elucidated the intricate molecular mechanism by which ZEB1 promotes CRC." (PMID 39193340, 2024). "This vulnerability is manifested in different drug-resistant cancer cells, including ZEB1-driven cells which are susceptible to epithelial-mesenchymal transition (EMT)." (PMID 38711989, 2024). "Here, we have studied the role of ZEB1 in fibroblasts using mouse models for colitis-associated cancer and sporadic metastatic CRC demonstrating a key requirement for CAF diversification." (PMID 38937629, 2024). "Unlike USP39, which hinders the degradation of ZEB1 by deubiquitination, TRIM26 carries out its cancer-causing role by promoting the degradation of ZEB1 through ubiquitination." (PMID 38956921, 2024). "Regarding EMT as a cancer hallmark, recent reports demonstrate that efficient invasion and metastasis require the expression of ZEB1 and SNAIL." (PMID 39030166, 2024). "Recent data indicate that ZEB1 is a critical player in cancer progression, and its expression has been associated with poor differentiation, aggressive disease, metastatic development, and poor clinical prognosis across various cancer types." (PMID 39722890, 2024). "While reprogrammed cellular metabolism is a widely accepted hallmark of cancer, our study adds to this by reporting for the first time that ZEB1 significantly enhances glycolysis in CRC cells." (PMID 39193340, 2024). "By inducing epithelial-mesenchymal transition (EMT), ZEB1 endows cancer cells with proinvasive and stem-like properties, which are strongly associated with poor clinical prognosis in the majority of human cancers." (PMID 39736693, 2024). "ZEB1 is a well-known inducer of EMT and high ZEB1 levels are associated with a higher invasive capacity of cancer cells, whereas invasion is impaired upon ZEB1 knock-down." (PMID 38139138, 2023). "We explored the relationship between lncRNA HOTAIR and three important molecules, TGF-β1 and ZEB1 and E-cadherin, which are associated with cancer progression, metastasis and epithelial-mesenchymal transformation (EMT)." (PMID 38070058, 2023).
cancer (continued). "The high-level profile of Zinc-finger E-box binding protein 1 (ZEB1), a transcription factor, is strongly linked to cancer malignancy." (PMID 37827696, 2023). "Mechanistically, the YAP-ZEB1 interaction can shift ZEB1 from a transcriptional repressor to an activator, thereby stimulating the transcription of cancer aggressiveness-associated genes." (PMID 37211598, 2023). "The divergent findings in VIP and ZEB1 expression associations between tissues (healthy and malignant) and cancer cell lines highlight the need for future studies in both settings." (PMID 37444395, 2023). "Zinc finger E-box-binding homeobox 1 (ZEB1) is a critical activator of the EMT associated with cancer." (PMID 37373414, 2023). "PTAR-associated upregulation of ZEB1 EMT-associated TF was observed in mesenchymal sub-types as compared to epithelial sub-types in The Cancer Genome Atlas (TCGA) OC data sets." (PMID 37464436, 2023). "Currently reported underlying mechanisms of LAMC2-induced cancer cell progression and metastasis include regulation of integrin B1-, ZEB1, and Snail expression, as well as activation of AKT1 and EGFR." (PMID 37542131, 2023). "ZEB1 associates with poorer survival in most carcinomas, including CRCs; however, the role of ZEB1 in BRAF-mutant CRCs or a potential differential role of ZEB1 in CRCs based on the mutational status have not been explored." (PMID 37870961, 2023). "One study of 117 patients with pancreatic ductal adenocarcinoma revealed that patient prognosis is inversely correlated with the levels of ZEB1 expression in stromal cancer-associated fibroblasts." (PMID 35454770, 2022). "ZEB1 has also been shown to be associated with tumorigenesis and chemoresistance in various human cancers." (PMID 36512117, 2022). "We also discovered that the induction of ZEB1 expression leads to the coexistence of subpopulations of epithelial, mesenchymal-like, and hybrid cell states expressing factors associated with cancer cell migration and invasion." (PMID 35440541, 2022). "Zinc finger E-box-binding homeobox gene 1 (ZEB1) is a transcriptional factor (TF) demonstrated to be associated with gene control in numerous varieties of cancer cells regarding invasion, migration, epithelial–mesenchymal translation (EMT), and proliferation." (PMID 35464451, 2022). "The expression of the ZEB1 in the nucleus was found to be significantly higher in sarcomatous components than that in cancer components in all three cases, suggesting an association of HCS with EMT." (PMID 36172159, 2022). "EMT is essential in cancer development and CSCs and Zeb1 have been implicated in the expression of several stem cell-associated transcription factors, including those with oncogenic potentials, such as BMI1, KLF4 and SOX2." (PMID 35404029, 2022). "Significantly, increased expression of either of Zeb1 and/or Zeb2 has been found to be associated with poor clinical outcome in various cancer types including breast, colorectum, pancreas, ovarian etc." (PMID 34708244, 2022). "The induction of EMT can be triggered by transcription factors, such as ZEB1, whose expression increases with cancer stages and is associated with aggressive disease and poor prognosis in colon cancer." (PMID 35884974, 2022). "Genetic deletion of Zeb1 in PDAC cells also leads to liver metastasis associated with cancer cell epithelial stabilization." (PMID 33852841, 2021). "In cancer, one cause of downregulation of E-cadherin is abnormal overexpression of zinc finger E-box-binding homeobox 1 (ZEB1)." (PMID 34210327, 2021). "In cancer, ZEB1 has been implicated in the regulation of early dissemination, metastasis, and therapy resistance." (PMID 34439395, 2021). "Similar to the dual loss of Snail and Twist, which reduce the cancer cell expression of Zeb1, we also observed the stabilization of an epithelial phenotype." (PMID 33852841, 2021).